ENSG00000257391 (microRNA 3180-4)
Gene: Long non-coding RNA gene on chromosome 16 (15,152,454 to 15,163,390, forward strand). Ensembl gene ENSG00000257391.
Gene Ontology:
Biological process: miRNA-mediated post-transcriptional gene silencing